ALB (albumin)
Diseases named in the same sentence as ALB in open-access papers (continued):
Sharing a sentence is not in itself a finding about the gene and the disease.
cancer (continued). "It has been well manifested that the albumin level is related to the development, progression and prognosis among cancer patients." (PMID 38216656, 2024). "In this study we have assessed the affinity of antibodies against estrogenized human serum albumin, given that estrogenized proteins are frequently observed in cancer patients, and HSA which is the most abundantly found protein in blood." (PMID 39664179, 2024). "Currently, the role of recombinant albumin and albumin nanocarriers in drug delivery and cancer therapy is being extensively studied." (PMID 38500655, 2024). "Serum albumin can be used as an indicator of nutritional status to assess the survival rate of cancer patients." (PMID 39668902, 2024). "Among albumins, bovine serum albumin (BSA) and human serum albumin (HSA) are widely studied for drug delivery and have gained significant attention in cancer diagnosis and therapy." (PMID 39770409, 2024). "Many NP-based cancer medications have been evaluated or applied in clinical trials, for example, NP albumin-bound-paclitaxel is one of the most widely used nano-medication in cancer treatment." (PMID 39600709, 2024). "At baseline, patients with cancer had lower prealbumin and albumin levels (p< 0.001), higher CRP levels (p < 0.001), and lower UAMA percentiles (p = 0.0245) compared with controls." (PMID 39619813, 2024). "A decrease of 1-SD in serum albumin levels corresponded to HR of 1.16 (1.09–1.22), 1.16 (1.05–1.28), and 1.13 (1.03–1.23) for total, vascular and cancer mortality, respectively." (PMID 39010980, 2024). "In this study, we utilized the NHANES (1999-2018) database to enroll a total of 4430 cancer patients in order to analyze the relationship between serum albumin levels and cancer mortality." (PMID 38500655, 2024). "It is worth emphasizing again that Nab-sirolimus (albumin-bound sirolimus nanoparticle) has been approved by the FDA for clinical use against human cancers." (PMID 39410026, 2024). "Definitive serum albumin levels were available for 21 of the 23 patients with NS induced by cancer therapy and were normally distributed." (PMID 38965515, 2024). "Previous studies have demonstrated that serum ALB has prognostic significance in several kinds of cancers, including lung cancer, gastrointestinal cancer, breast cancer, ovarian cancer, and NPC." (PMID 38915379, 2024). "Albumin serves as a key indicator of nutritional status and overall health, factors known to influence cancer prognosis." (PMID 39600700, 2024). "Several studies on patients with malignant tumors have shown that the GNRI is more advantageous than serum albumin levels, body weight, or BMI alone for prognostic evaluation." (PMID 38997737, 2024). "Capitalizing on the fact that albumin can be internalized by tumors as a nutrient, albumin-based nanotherapeutics have been developed for cancer therapy." (PMID 39479443, 2024). "Albumin has been used as a biomarker in cancer cachexia trials since at least 1993 and is still used today." (PMID 38783477, 2024). "Substantial evidence suggests that parameters reflecting nutritional and inflammatory status, including albumin and hemoglobin levels and lymphocyte and platelet counts, are critical for cancer survival." (PMID 39744624, 2024). "Low levels of serum albumin and lymphocytes can promote inflammatory tumor development and cancer spread." (PMID 38400912, 2024). "Significant differences in smoking history, the pathological diagnosis of cancer, serum albumin concentration, and platelet count were noted between the two groups." (PMID 39272789, 2024). "Serum albumin/prealbumin are considered adequate laboratory markers of nutritional status in cancer patients, with a correlation to outcome." (PMID 38539369, 2024). "Cancer control rats (B) showed significantly lowest plasma proteins with 76.66 ± 2.9 and 68 ± 3.5 g/L concentrations for total protein and albumin, respectively." (PMID 38191592, 2024).
cancer (continued). "Serum CRP and albumin are two crucial acute-phase proteins that reflect the nutritional status during the systemic inflammatory response, which commonly occurs in malignant tumors." (PMID 38903332, 2024). "In the early stage of cancer, albumin levels are normal or slightly low, and they significantly drop when the disease progresses." (PMID 39771527, 2024). "Both albumin and globulin provide valuable insight into a patient's current overall health and immune status as they begin the process of fighting their cancer diagnosis." (PMID 38975562, 2024). "The analysis of KEGG pathways also revealed that the putative antihepatic cancer targets identified (Akt1, EGFR, TNF, and ALB) are involved in multiple pathways associated with cancer development and progression." (PMID 39502516, 2024). "To date, most research on albumin-based drug carriers for cancer (e.g., Abraxane, aldoxorubicin) has focused on delivery of chemotherapy drugs that target cancer cells." (PMID 38766114, 2024). "PNI can be determined from total lymphocyte count and serum albumin level, which has been proven to be an effective prognostic marker for various malignant tumors." (PMID 39010005, 2024). "Serum albumin level serves as a critical indicator of nutritional status in cancer patients and is deeply intertwined with their cancer prognosis." (PMID 38500655, 2024). "They determined an optimal cutoff of albumin >3.7 g/dL across different cancer types, and this same cutoff was utilized in our study." (PMID 38911864, 2024). "CRP and ALB are vital acute-phase proteins reflecting the body’s nutritional state during systemic inflammatory responses and are pivotal in predicting cancer patient survival." (PMID 39410928, 2024). "The new albumin–NLC–SambucusN arrested cancer cells in G1 and G2 cycles and intensified the apoptosis process in both early and late phases." (PMID 39456987, 2024). "A study integrated an Evans Blue-modified Sgc8 (EB-Sgc8) with human serum albumin (HSA) to fabricate more effective anti-cancer drugs." (PMID 39474113, 2024). "In the search for new and so far unexplored immunosuppressor mechanisms in cancer, it was found that albumin neo-structures generated by proteolytic fragmentation had immunoregulatory activities such as the stimulation of IL-6 synthesis." (PMID 39518029, 2024). "Hepatic proteins, including albumin, prealbumin, and transferrin have been confirmed to be prognostic predictors in various cancers." (PMID 38438901, 2024). "As a result, age, BMI, DM, CVD, cancer, urine volume, HGB, ALB, and PE remained independent predictors of all-cause mortality." (PMID 38415296, 2024). "Albumin has been used in many drug delivery systems, including cancer-targeted drug delivery systems." (PMID 39458651, 2024). "The study population was stratified into two groups based on median albumin levels (≤ 4.2g/dL and > 4.2 g/dL) or cancer aggressiveness (well-survived cancers and poorly-survived cancers)." (PMID 38500655, 2024). "In our study, prealbumin and albumin levels were also significantly lower in children at the time of cancer diagnosis compared with healthy control." (PMID 39619813, 2024). "Low albumin, prealbumin, and transferrin levels were all independent prognostic factors affecting patients with cancer cachexia, especially in patients in the advanced stages." (PMID 38438901, 2024). "ALBI and PALBI grades can indicate cancer prognosis since they consist of albumin and bilirubin levels and platelet count." (PMID 38228667, 2024). "The prognostic nutritional index (PNI) is a measurement calculated using albumin and absolute lymphocyte value, reflecting the immunological and nutritional status of the cancer patient." (PMID 39161499, 2024). "In this study, we synthesized, characterized, and explored the anti-microbial and anti-cancer effects of albumin–chlorogenic acid nanoparticles (NPs)." (PMID 37176983, 2023).
cancer (continued). "A 15% decrease in plasma albumin levels, as reported in cancer populations, has been implemented in the default cancer population model." (PMID 38140068, 2023). "The PNI score is calculated from albumin and lymphocyte counts and is a simple method for the assessment of the immune‐nutritional status of cancer patients." (PMID 37930138, 2023). "Among the broad spectrum of methods to assess nutritional status in cancer, serum ALB levels have emerged as one of the most accurate." (PMID 37762957, 2023). "The imbalance of protein and energy metabolism in patients with cancer leaves the level of albumin in an imbalanced state." (PMID 36444689, 2023). "A meta-analysis by Nagaraja showed that ES led to the relief of dysphagia, weight gain, and higher albumin levels at follow-up in cancer patients." (PMID 36986253, 2023). "PNI, which is a marker that can be easily calculated using serum albumin levels and peripheral blood lymphocyte counts, is an important biomarker that has been proven to affect survival in various cancer types." (PMID 37685501, 2023). "ALB (serum albumin) is an important indicator for monitoring the nutritional status of cancer patients." (PMID 37764733, 2023). "Among them, albumin’s antioxidant properties play a crucial role in critical pathologies such as cancer by balancing the plasma redox state." (PMID 37571238, 2023). "Several studies on patients with malignant tumors have shown that compared with the use of serum albumin levels, body weight, or body mass index (BMI) alone, the GNRI is advantageous in prognostic evaluation." (PMID 36815992, 2023). "Various cytokines such as IL-6 and TNF can increase catabolism and reduce albumin synthesis in cancer patients." (PMID 37143476, 2023). "Albumin itself can bind to receptors overexpressed by cancer cells of particular types, such as the 60 kDa glycoprotein (gp60) receptor and secreted protein acidic and rich in cysteine (SPARC)." (PMID 36678860, 2023). "Many pro-inflammatory cytokines, such as IL-1, IL-6, and TNF- α, are involved in regulating the production of albumin in hepatocytes, and they also play a particular role in regulating angiogenesis and cancer progression." (PMID 37197434, 2023). "Albumin conjugation to the chemotherapeutic drugs like paclitaxel and docetaxel were well studied for its enhanced cancer delivery." (PMID 37986071, 2023). "As proof‐of‐concept application in cancer therapy, the nanometric protein–drug conjugate strategy was combined with an acid‐sensitive prodrug strategy to produce an albumin and doxorubicin conjugate: NanoAlb‐proDOX." (PMID 36684090, 2023). "Prior studies have consistently shown a strong correlation between low serum albumin levels and poor prognostic outcomes in individuals with malignant tumors." (PMID 37787070, 2023). "Although underlying mechanisms remain controversial, the role of serum albumin as a predictor of cancer survival remains indisputable." (PMID 36924334, 2023). "Although patients with cancer are likely to have low albumin and fewer lymphocytes, elderly patients undergoing PLIF surgeries in the present study were less likely to have these conditions." (PMID 37629374, 2023). "Despite the low blood pressure within the tumors, lymphatic insufficiency and blood vessel leaks play a role in making blood serum or its albumin protein accessible to cancer cells." (PMID 36597205, 2023). "For all three types of cancer cells (MCF-7, HeLa and MDA-MB-231), the albumin-based hydrogel containing DOX caused about 70%–80% of cell death." (PMID 37113668, 2023). "Pretreatment serum albumin levels provide useful nutritional assessment and prognostic significance for cancer patients." (PMID 36941480, 2023). "In this study, we constructed a nomogram prediction model for VTE risk including KPS, stage of cancer, varicosity, COPD, CVC, albumin, PT, leukocyte counts, EGFR-TKI, dexamethasone, and bevacizumab." (PMID 36872336, 2023).
cancer (continued). "Serum C-reactive protein (CRP) and albumin levels are representative of chronic inflammation and nutritional status in cancer patients." (PMID 37333829, 2023). "Serum albumin is a simple and inexpensive marker of systemic inflammation, as well as a surrogate for nutritional status and a strong prognostic factor in cancer patients." (PMID 37371699, 2023). "Abraxane that is composed of human serum albumin (HSA) and paclitaxel with size around 130 nm has achieved huge success in clinic to reduce the side effects in diverse cancers." (PMID 36815900, 2023). "We also set out to evaluate the prognostic value for other markers of cancer progress such as fatigue, change in albumin levels and CRP/albumin ratio." (PMID 37880704, 2023). "As a proof‐of‐concept application in cancer therapy, a nanometric albumin–doxorubicin prodrug conjugate (NanoAlb‐proDOX) was prepared." (PMID 36684090, 2023). "A number of inflammatory indicators are reportedly prognostic factors of cancers, including the C-reactive protein-to-albumin ratio, neutrophil-to-lymphocytes ratio, and others." (PMID 37592262, 2023). "Albumin-based nanoparticles have already been developed for the treatment of cancer, diabetes, hepatitis C, and arthritis." (PMID 36834596, 2023). "In this context, albumin, one of the most abundant proteins in the blood, has also been proposed as a large molecule to be conjugated with anti-cancer small-molecule drugs." (PMID 37049985, 2023). "The effect of albumin-paclitaxel is increased because the nanocarriers deliver the drug quickly to cancer tissue and stay there longer." (PMID 37270638, 2023). "The development of albumin-based drug delivery systems with controlled and targeted drug delivery is gaining increased importance in cancer therapy." (PMID 37836018, 2023). "Albumin’s interactions encompass key proteins involved in cancer cell invasion, like matrix metalloproteinases (MMPs) and urokinase-type plasminogen activator (uPA)." (PMID 37987317, 2023). "The high PNI was also correlated with better anti-cancer therapy response and performed better than body mass index and serum albumin level in OS prediction." (PMID 37575320, 2023). "In the past, serum albumin and BMI were widely used to evaluate the nutritional condition of cancer patients." (PMID 37380982, 2023). "When we focus on the most severe cancer stages (Iva, IVb and IVc), only albumin and transferrin had a significant difference, decreasing as the severity of the cancer stage increases." (PMID 36771369, 2023). "This score, calculated from serum albumin, total lymphocyte count, and total cholesterol, has recently emerged as a tool to assess the nutritional and immunological status of patients with malignancies." (PMID 37642856, 2023). "Previous investigations have reported that controlling nutritional (CONUT) status scores, incorporating total cholesterol (TC) and serum albumin (SA) values, and total lymphocyte (LY) counts, are reliable malignant tumor predictors." (PMID 37182171, 2023). "GPS, the ratio between CRP and albumin, has been extensively validated as a biomarker of poor prognosis in cancer." (PMID 37213604, 2023). "HALP score, composed of lymphocytes, albumin, hemoglobin and platelets, has recently been employed for predicting the prognosis of patients suffering from different forms of cancers." (PMID 37786581, 2023). "There was statistically significant decreased mean level of serum albumin, Hgb and TP in malnourished as compared with well-nourished patients with cancer." (PMID 36869395, 2023). "The ratio of serum globulin to albumin(GAR) has been used to predict the prognosis of patients with various cancers." (PMID 39077558, 2023). "This is in line with our results where patients diagnosed with various cancer types, that had an albumin level ≤ 36 g/L, also had a shorter survival time than patients with higher albumin values." (PMID 37880704, 2023).
cancer (continued). "The PD-L1-targeted albumin nanoparticle loaded with PTX (PD-L1/PTX@HSA) was used for combinational chemo-immune therapy and showed enhanced drug release at low pH levels in cancer cells." (PMID 36986636, 2023). "In cancer patients, the systemic inflammatory response induces increased peripheral blood cell numbers and decreased serum albumin levels." (PMID 37270496, 2023). "Changkyu Lee and Sebyung Kang used the SpyTag*SpyCatcher ligation system to modify albumin nanoparticles for targeted delivery to cancer cells." (PMID 36678860, 2023). "Increased proinflammatory cytokines, in addition to lower serum proteins like albumin, seen in cancer patients are instrumental in developing cachexia." (PMID 36848404, 2023). "It is widely acknowledged that the serum albumin level reflects the nutritional status of cancer patients, and it is known negatively correlate with systemic inflammatory response." (PMID 37211905, 2023). "The prognostic role of the CRP level has also been assessed in combination with the albumin level in the mGPS, an inflammatory/nutritional index, which is the most validated prognostic index in patients with cancer." (PMID 36831431, 2023). "Cancer-related inflammation can impair albumin synthesis through changes in cytokine production that increase microvascular permeability." (PMID 36674837, 2023). "CAR and the modified Glasgow and prognostic score, which comprises CRP and albumin concentrations, have been shown to have prognostic value for several cancers." (PMID 36875089, 2023). "Serum albumin levels, a classic nutrition index, were also considered an inflammation related factor and reported as a prognostic marker for cancer in many studies." (PMID 37270496, 2023). "Albumin can be used to reflect the nutritional and systemic inflammatory status of cancer patients and can be used as a prognostic marker for diverse cancers." (PMID 37491191, 2023). "The NRI is a comprehensive index based on albumin and weight and has been widely used in recent years to assess prognosis in cancer." (PMID 36441260, 2023). "Since systemic inflammation is a hallmark of cancer cachexia, and because LCN-2 release is associated with inflammation, we determined the degree of systemic inflammation as expressed by the CRP to albumin ratio in the study groups." (PMID 37006254, 2023). "Albumin, a major protein in human serum, has been used to evaluate nutritional status, and low albumin levels have been shown to be related to poor prognosis in patients with various cancers." (PMID 36441260, 2023). "Serum albumin (ALB), a classical biomarker of the body’s nutritional status, can reliably assess the nutritional status of cancer patients." (PMID 38066499, 2023). "FcRn’s promising features in cancer treatment and molecular diagnosis are rooted in its abilities of albumin recruitment and the transcytosis of immunoglobulins, extending the half-life of cancer drugs and antibody-based therapeutics." (PMID 38132243, 2023). "The ALB content in healthy individuals was mainly concentrated at 45 mg/ml, while that in cancer patients was relatively low at 45 mg/ml." (PMID 36776604, 2023). "We have chosen to discuss serum albumins and albumin-based nanoparticles because they have been mentioned as having suitable properties and an essential role in cancer targeting, especially in brain cancer." (PMID 37836018, 2023). "In this study, we constructed a novel nanotherapeutic agent (PDL1-NP-FEXO) for cancer immunotherapy by attaching PD-L1 aptamers to albumin nanoparticles that were loaded with H1-antihitamine fexofenadine (FEXO)." (PMID 36985529, 2023). "In recent years, macropinocytosis has emerged as an important mechanism for amino acid nutrition in cancer cells in which extracellular proteins such as albumin can be taken up into cells and subsequently degraded in lysosomes to provide amino acids." (PMID 36765717, 2023).